AKT3 (AKT serine/threonine kinase 3)
Diseases named in the same sentence as AKT3 in open-access papers (continued):
Sharing a sentence is not in itself a finding about the gene and the disease.
melanoma (continued). "For example, upon the loss of PTEN, the invasiveness of human melanoma cell lines was enhanced through the preferential phosphorylation of AKT2, whereas AKT3 phosphorylation reduced the invasive potential of PTEN-null melanoma cells." (PMID 37894325, 2023). "Elevated expression of AKT3 was found in 50% of dysplastic nevi, and 70% of primary or metastasizing melanomas." (PMID 35621644, 2022). "A recent study identified WEE1 as a valid target to inhibit in combination with AKT3, a major target in melanoma." (PMID 35563772, 2022). "Inactivation of PTEN in human cancer results in upregulation of the AKT pathway (mainly AKT3 in melanoma) and its substrate mTOR, therefore mediating tumorigenesis." (PMID 35621644, 2022). "Using isoform-specific guide RNAs (gRNAs), we used CRISPR-Cas9 to knockout AKT1, AKT2, or AKT3 in multiple melanoma cell lines, validating the success of AKT knockout by Western blotting." (PMID 35158840, 2022). "In melanoma, AKT1 and AKT2 activation are more commonly found in BRAF-mutant tumors, while AKT3 hyperactivity is more common in BRAF wild-type melanomas." (PMID 35158840, 2022). "AKT3 has been described to be the AKT isoform predominantly upregulated in melanoma to guide full oncogenic transformation; the consequential activation of PI3K signalling allows for evasion of cell cycle arrest caused by BRAFV600E oncogene induced senescence." (PMID 33673003, 2021). "AKT3 as one of three AKT family members seems to play an important role in promoting the development of malignant melanomas, triple negative breast cancer, colorectal cancer and it is also expressed in prostate carcinoma." (PMID 33540707, 2021). "Although the AKT signaling pathway is frequently activated in melanoma progression, the loss of PTEN predominantly precedes the activation of AKT3." (PMID 32878000, 2020). "AKT3 is upregulated in malignant melanomas and is uniquely necessary among AKT isoforms for cranial development." (PMID 32977414, 2020). "In melanoma brain metastasis, AKT1 and AKT3 are sites of mutation and the expression of AKTe17k seems to be connected with the higher probability of melanoma brain metastases (MBMs) and shorter survival in the murine model." (PMID 32575838, 2020). "Recently, Akt3 and Wee1 (a protein involved in cell cycle regulation) have been defined as putative and simultaneous targets to synergistically inhibit melanoma in vitro." (PMID 30166456, 2018). "Deregulated Akt activity has been shown to be responsible for 35–70% of advanced metastatic melanomas, and the majority of melanomas have elevated Akt3 expression and activity." (PMID 29367689, 2018). "Akt3 is predominantly activated in a number of cancers such as malignant melanoma and glioma, and plays important roles in the survival of immortalized MEFs." (PMID 28483982, 2017). "One of the key effector proteins in this pathway is known as PKB (protein kinase B) or AKT, which has three isoforms (AKT1, AKT2, and AKT3), with AKT3 being found frequently activated in melanomas." (PMID 28430130, 2017). "Increased expression of AKT3 is present in 50% of dysplastic nevi, 70% of primary melanomas, and 70% of metastases." (PMID 26322273, 2015). "In a separate study, the specific knock-down of AKT3 reduced the level of phosphorylated Akt and inhibited cell growth in malignant melanoma." (PMID 25997610, 2015). "Constitutive activation of the PI3K pathway occurs in approximately 70% of sporadic melanomas due to the loss of PTEN and/or amplification of AKT3." (PMID 25595898, 2015). "Here we show for the first time that TBX3 is a novel direct substrate of AKT3 that mediates its role, in part, in melanoma progression." (PMID 25595898, 2015). "In conclusion, we show that TBX3 is a novel direct substrate of AKT3 that mediates its invasive role, in part, by repressing E-cadherin during melanoma progression." (PMID 25595898, 2015).
melanoma (continued). "Of the three AKT isoforms, AKT3 is reported to be the one that is predominantly active in melanoma formation." (PMID 25595898, 2015). "High PIP3 levels sequentially activate downstream AKT (mainly, AKT3 in melanoma) and its substrate mTOR, modulating the synthesis of proteins involved in cell growth and survival as well as in apoptosis." (PMID 26322273, 2015). "AKT3 is the predominant isoform in melanomas where it plays a critical role in invasion, metastasis and therapeutic resistance." (PMID 25595898, 2015). "We would like to thank Prof Dorothy Bennett for the melanoma cell lines, Prof Colin Goding for critical reading of this manuscript, Dr Amaal Abrahams and Melanie Oesterle for general assistance for the AKT3 kinase assay and luciferase assays respectively." (PMID 25595898, 2015). "This indicates that the AKT3/PI3K pathway is activated during progression to malignant melanoma, most likely as a means of overcoming OIS." (PMID 24743024, 2014). "A screen of 137 melanomas and 65 cell lines identified an activating mutation E17A in AKT1 (one patient) and AKT3 (one patient and two cell lines), all with concurrent BRAF mutations." (PMID 24743024, 2014). "Akt3 expression is increased as a result of elevated gene copy number in ~50% and ~70% of primary melanomas and metastatic melanomas, respectively." (PMID 25168062, 2014). "In support of this notion, while BRAF mutations are present in both nevi and melanoma sections of contiguous nevi-melanoma biopsies, activation of PI3K (through loss of PTEN expression or activation of AKT3) was detected in the melanoma portions only." (PMID 24743024, 2014). "Deregulated Akt3 activity was shown to promote development of malignant melanoma; amplifications of Akt3 were detected in melanoma." (PMID 24743024, 2014). "A potential target of miR-125b is Akt3, which is overactive in melanoma and whose expression increases during melanoma progression." (PMID 24047116, 2013). "For instance, 70% of biopsies derived from patients with melanoma exhibited abnormal activities in the PI3K/Akt3-related signaling system." (PMID 24381788, 2013). "A subsequent report showed that an enhanced PI3K/Akt3 pathway activity is one of the main contributors in the genesis of melanoma." (PMID 24381788, 2013). "AKT3 activation is found in about 60% of sporadic melanomas subsequent to gene amplification (35% of the cases) or to inactivation of PTEN (40–60% of the cases), which negatively regulates the PI3K/AKT pathway." (PMID 24416617, 2013). "Overexpression of AKT1 and AKT3 has only been shown in human gastric cancer and melanoma, respectively." (PMID 22666248, 2012). "AKT3 activity is commonly increased in melanoma, and it is directly responsible for resistance to apoptosis." (PMID 22927992, 2012). "Copy gains of the AKT3 gene are found in about 60% of melanomas and are correlated with melanoma progression." (PMID 22216021, 2012). "siRNA knockdown of PTEN led to enhanced AKT3 phosphorylation in both melanocytes and human melanoma cells." (PMID 23372575, 2012). "Novel cationic nanoliposomes stably encapsulate siRNA targeting (V600E)B-Raf or Akt3, providing protection from degradation and facilitating entry into melanoma cells to decrease expression of these proteins." (PMID 22623890, 2012). "siRNA knockdown of wild-type PTEN has been shown to result in increased phosphorylation of AKT3 and radial growth reinforcing its involvement in melanoma pathogenesis." (PMID 23372575, 2012). "The deletion or silencing of PTEN increases the level of AKT3 phosphorylation in melanocytes and early stage melanoma cells." (PMID 22216021, 2012). "Recently, a nanoliposomal-ultrasound-mediated approach reported for delivering small interfering RNA (siRNA) specifically targeting (V600E)B-Raf and Akt3 into melanocytic tumors present in skin to retard melanoma development." (PMID 22623890, 2012).
melanoma (continued). "AKT3 expression strongly correlates with melanoma progression, and depletion of AKT3 induces apoptosis in melanoma cells and reduces the growth of xenografts." (PMID 19828018, 2009). "Of the three AKT family members (AKT1–3), about 50% of melanoma cells have constitutive activity in AKT3." (PMID 19156138, 2009). "It has been proposed that a common mechanism of activation of AKT is DNA copy gain involving the AKT3 locus, which is found in 40-60% of melanomas." (PMID 19828018, 2009). "We analysed melanoma clinical specimens for the presence of mutations in AKT1, AKT2, and AKT3 that result in the E17K mutation identified previously in breast, ovarian, and colorectal cancers." (PMID 18813315, 2008). "In addition, the role of Akt3 in mediating PRAS40 phosphorylation was reported in malignant melanoma." (PMID 39611167, 2024). "By contrast, even though mutations in the catalytic subunit of PI3K, or AKT1, AKT2, and AKT3, are rare in melanoma, immunopositivity of AKT3 is common in melanoma, and could activate PI3K–AKT–mTOR in PTEN wild type tumors." (PMID 36135270, 2022). "As with the two other isoforms, AKT3 is not often reported to be activated through genetic events; infrequent AKT3 activating E17K mutations have been identified in melanoma samples." (PMID 33673003, 2021). "High-level expression of Akt3 has been reported in some melanomas and may contribute to vemurafenib resistance." (PMID 33549048, 2021). "Additionally, it has been demonstrated by Lin and colleagues that AKT3 has an effect on PCa cell line proliferation and AKT3 is overexpressed in malignant melanomas, supporting cell survival as well as mediating apoptosis resistance in melanoma cells." (PMID 33540707, 2021). "In addition to self-renewing factors studied in our systematic analysis of gene expression in CD271+ melanoma-initiating cells, a significant upregulation of the major pro-survival network controlled by AKT3 was uncovered." (PMID 31118427, 2019). "It is reported that AKT3 is overexpressed in glioma, melanoma, and ovarian cancer." (PMID 31160577, 2019). "Using system pathway profiling analysis we reveal the molecular network model, which illustrates how different neurotrophin receptor-dependent adaptor proteins, including GRB2, SHC, and GAB1 connect activation of CD271 to the upregulation of AKT3 in CD271+ melanoma-initiating cells." (PMID 31118427, 2019). "AKT3 plays a major role in neuronal development and shows an enhanced activity in many melanomas." (PMID 30755508, 2019). "The Akt3 signaling pathway is deregulated in about 70% of advanced stage melanoma." (PMID 28978182, 2017). "In addition, patients with very high AKT3 expression (H Score > third quartile H Score) in the primary tumor presented significantly worse melanoma-specific and progression-free survival than the other patients (low to moderate expression)." (PMID 28578692, 2017). "Targeting a direct substrate(s) of AKT3 may therefore hold greater promise in the treatment of melanomas." (PMID 25595898, 2015). "However, mutations in BRAF alone rarely trigger melanoma and additional genetic events in BRAF-mutant cells, such as activation of AKT3, elicit a fully cancerous phenotype." (PMID 25595898, 2015). "The AKT3 signalling pathway plays a critical role in melanoma formation and invasion and components of this signalling cascade are therefore attractive targets for the treatment of malignant melanoma." (PMID 25595898, 2015). "While AKT3 substrates involved in mediating its impact on proliferation, apoptosis and chemo-resistance in melanoma have been identified, our study is the first to reveal a direct substrate involved in AKT3-induced melanoma migration." (PMID 25595898, 2015). "High activity of AKT3 was shown to promote progression of BRAFV600E-positive nevi to melanoma." (PMID 24743024, 2014).
melanoma (continued). "To address whether the observed AKT activation could be the reason for conveying the anti-apoptotic effect, we overexpressed constitutively active myristoylated AKT3 (myrAKT3) in melanoma cell lines." (PMID 24970815, 2014). "Alterations of AKT1 and AKT2 are rare, but genetic gain of Akt3 is seen in 25% of melanoma tumors." (PMID 24743024, 2014). "Some studies showed an involvement of aberrant PI3K/Akt3 activity in human melanoma." (PMID 24381788, 2013). "In melanoma cells, AKT3 is the form preferentially expressed." (PMID 24416617, 2013). "AKT2 and AKT3 have emerged as the predominant forms that are dysregulated in melanoma." (PMID 23372575, 2012). "Notably, several studies have reported that Akt3 promotes melanoma development and that the down-regulation of Akt3 distinctly inhibited the proliferation of ovarian cancer cell lines by slowing G2-M phase transition." (PMID 22051041, 2011). "Further support for the role for AKT signaling in intrinsic BRAF inhibitor resistance came from other studies showing that overexpression of an active form of AKT3 (myristolated AKT3) prevented apoptosis in BRAF V600E mutant melanoma cells when BRAF was inhibited." (PMID 21505227, 2011). "Moreover, AKT3 also plays a pivotal role in melanoma tumorigenesis and drug resistance." (PMID 40681872, 2025). "Here, we show that prolonged exposure of BRAF-mutant melanoma cells to vemurafenib treatment leads to the emergence of drug-resistant melanoma subpopulations characterized by an increase in CD271 expression with induced Akt3 and Nox4 activity and the subsequent EMT process." (PMID 37189846, 2023). "Indeed, in melanoma, AKT3 is the most abundant isoform and AKT phosphorylation of TBX3 enhances protein stability, nuclear localisation and transcriptional activity; in fibrosarcoma and chondrosarcoma, AKT1 is the predominant isoform and it maintains high levels of TBX3." (PMID 32098189, 2020). "Targeted inhibition of Akt3 in melanoma cell lines could decrease the pAkt level significantly." (PMID 29367689, 2018). "However, Akt (mainly Akt3) is overexpressed in 43–60% of non-familial melanomas, and it has been implicated in disease progression, metastasis, and development of drug resistance." (PMID 30166456, 2018). "Downregulation of miR-125b may contribute to progression of melanoma via Akt3 upregulation." (PMID 24047116, 2013). "Interestingly, while PTEN loss is found at high frequency in melanoma (37%) but not in nevi, AKT3 activity level increases with advancing melanoma stage." (PMID 24416617, 2013). "Additionally, levels of phosphorylated AKT3 were found to correlate with melanoma progression suggesting that AKT3 might have a role in the aggressiveness of melanomas." (PMID 23372575, 2012). "Collectively, these results indicate that the activation of AKT3 mediated by SYK is crucial for the elevation of ROS and induction of cell death upon glucose deprivation in melanoma cells." (PMID 40774947, 2025). "AKT3 promotes resistance to apoptosis in BRAF-targeted melanoma cells, and FGF/FGFR signaling supports melanoma survival and therapy resistance." (PMID 41000875, 2025). "The combined inhibition of AKT3 and WEE1 kinases synergistically inhibited cellular proliferation and induced apoptosis in melanoma cells." (PMID 35563772, 2022). "PHLPP1 inhibits melanoma metastasis through its phosphatase activity, repressing AKT2 and to a lesser extent AKT3." (PMID 35008286, 2021). "Alterations in other important constituents of the PI3K/AKT pathway, namely RAC1, PIK3CA, AKT3, PREX2, and AKT1, are also known to occur in melanoma." (PMID 35008286, 2021). "miRNA-224-5p can be regulated by E2F1 to drive EMT through TXNIP downregulation in melanoma, and it can inhibit uveal melanoma cell proliferation, migration, and invasion by targeting PIK3R3/AKT3." (PMID 32993558, 2020).
melanoma (continued). "Rhabdomyosarcomagenesis involves, in part, the prolonged activation of serine/threonine kinases such as AKT, and we have previously shown that AKT1 and AKT3 phosphorylation stabilizes the TBX3 protein in chondrosarcoma/fibrosarcoma and melanoma, respectively." (PMID 32098189, 2020). "Majority of melanoma samples with elevated Akt activity also show corresponding higher levels of PRAS40 phosphorylation, and siRNA-mediated inhibition of Akt3 reduces the levels of PRAS40 phosphorylation." (PMID 28978182, 2017). "AKT3 is involved in 8 of the 10 identified pathways – Dopaminergic synapse, Rap1 signaling, Focal adhesion, MAPK, Melanoma, Proteoglycans in cancer, PI3K-AKT, and Ras signaling." (PMID 29321820, 2017). "Our results identify a novel signalling and transcriptional network linking AKT3, TBX3 and E-cadherin during melanoma migration and invasion and reveals TBX3 as a potential target for anti-metastatic therapeutics." (PMID 25595898, 2015). "Next, we searched for CNAs in genes known to be affected by CNAs in melanoma (BRAF, KIT, MITF, CCND1, CDK4, PTEN, CDKN2A and AKT3)." (PMID 24399611, 2014). "There is also evidence that siRNA knockdown of AKT3 and BRAF V600E leads to the enhanced inhibition of melanoma xenograft growth in nude mice." (PMID 19156138, 2009). "Inhibition of AKT activity in melanoma, using either PI3K inhibitors or selective RNAi to AKT3, or both, reduces growth and induces some degree of apoptosis." (PMID 19156138, 2009). "Indeed, TBX3 has been shown to be regulated by AKT3 and AKT1 (key mediators of PI3K signalling) through posttranslational phosphorylation resulting in stabilisation and nuclear localisation in melanoma and fibrosarcoma cells respectively." (PMID 39403898, 2024). "By using a conventional in vitro wound healing assay, it was found that only AKT2 depletion and not AKT1 or AKT3 depletion inhibited cell migration in three different human melanoma cell lines." (PMID 37894325, 2023). "Recently, in CD271+ melanoma cells, Akt3 (unlike Akt1 and Akt2) was identified as the most expressed protein sustaining cell survival." (PMID 37189846, 2023). "We observed that AKT1 loss extended overall survival in melanoma-prone mice, while AKT2 and AKT3 loss did not." (PMID 37894325, 2023). "This is also consistent with our observation that tumor-derived cell lines consistently show robust phosphorylation of AKT1 when compared with other AKT isoforms, suggesting that AKT1 but not AKT2 or AKT3 plays a critical role in melanoma initiation." (PMID 37894325, 2023). "Since we did not observe changes in the expression of the validated miR-29 targets AKT3, MCL1, and DNMT3B, we identified new targets whose repression may contribute to restricting melanoma development." (PMID 33808771, 2021). "miR-29 may elicit its tumor suppressive potential by repressing targets such as AKT3, DNMT3A/B, or MCL1; however, miR-29 hairpin inhibitors failed to increase the expression of these validated targets in A375 melanoma cells." (PMID 33808771, 2021). "For example, AKT3 can make 40-60% non-hereditary melanoma cells survive, and inhibition of AKT3 activity promotes the death of these cells." (PMID 32520206, 2020). "Consistently, the stable shRNA-mediated knockdown of CD271 decreased the expression of AKT3, suggesting that the concerted action of CD271 and AKT3 may promote the melanocyte transformation and maintenance of early established melanoma cells." (PMID 32878000, 2020). "Hence, we further analyzed AKT1 and AKT3 mRNA expression by qRT-PCR in both PTEN+ and PTEN− melanoma cells." (PMID 31378787, 2019).